IQGAP3 (IQ motif containing GTPase activating protein 3)
Diseases named in the same sentence as IQGAP3 in open-access papers (continued):
Sharing a sentence is not in itself a finding about the gene and the disease.
breast carcinoma (continued). "Therefore, IQGAP3 may be a reliable novel biomarker to provide personalized prognostication in breast cancer and could be used to identify patients who may benefit from more aggressive RT treatment to improve their survival." (PMID 33519444, 2020). "Moreover, patients with high IQGAP3 expression were more likely to exhibit locoregional recurrence and distant metastasis, indicating that IQGAP3 protein expression promotes the progression of breast cancer." (PMID 33519444, 2020). "Therefore, IQGAP3 may be a reliable prognostic biomarker in breast cancer and could be used to identify patients who may benefit from radiotherapy." (PMID 33519444, 2020). "Therefore, IQGAP3 may be a potential therapeutic target in human breast cancer." (PMID 34675301, 2021). "For instance, IQGAP3, EPHB1, ROR2 and RCC2 were demonstrated to obviously promote cell migration, invasion, and epithelial-to-mesenchymal transition in hepatocellular carcinoma, medulloblastoma and breast carcinoma, respectively." (PMID 34922560, 2021). "Unlike IQGAP1 and IQGAP3, which function as oncogenes in breast cancer, the role of IQGAP2 is still unexplored." (PMID 33846302, 2021). "Multivariate survival analysis also indicated IQGAP3 expression was indeed an independent prognostic factor for OS and progression-free survival (PFS; p = 0.003 and p = 0.001, respectively) in the whole cohort breast cancer patients (n = 257)." (PMID 33519444, 2020). "We confirmed IQGAP3 was overexpressed both at the mRNA level (transcriptionally) and protein level (translationally) in breast cancer cell lines and human tumor samples compared to noncancerous breast epithelial cells and tissues." (PMID 33519444, 2020). "In addition, IQGAP3 is an independent negative prognostic factor for breast cancer." (PMID 36831467, 2023).
gastric cancer (12 papers, 2014 to 2025). A primary or metastatic malignant neoplasm involving the stomach. "Mutation analysis of IQGAP3 showed high frequency of mutations in colorectal (5.2%), lung squamous cell carcinoma (7.3%) and stomach cancer (5.2%), where the frequency of copy number change was very low." (PMID 29073199, 2017). "Here it is noteworthy that one frequent mutation (V293I/X293_splice) was present in four stomach cancer cases, at the splice site of IQGAP3." (PMID 29073199, 2017). "In this study, we hypothesized that the up-regulation of IQGAP3 is associated with the invasion/migration of gastric cancer cells." (PMID 32824461, 2020). "In light of these findings, future large-scale studies are necessary to address whether higher expression of IQGAP3 is associated with poorer prognosis in gastric cancer patients, particularly in Asian populations." (PMID 32824461, 2020). "Interestingly, one frequent mutation (V293I/X293_splice) was present in four stomach cancer cases, at the splice site of IQGAP3." (PMID 29073199, 2017). "The increase of IQGAP3 was observed in gastric cancer samples compared with normal controls, mostly distributed on the cell membrane and cytoplasm." (PMID 36831467, 2023). "IQGAP3 promotes tumor migration and invasion in the ovarian and gastric cancers Inhibiting TYMS promotes the proliferation, migration, and invasion of the cervix." (PMID 36750200, 2023). "IQGAP3 is also correlated with metastasis of gastric cancer, and overexpression enhances cell migration and invasion and reduces cell–cell adhesion." (PMID 36831467, 2023). "They found IQGAP3 is overexpressed in gastric cancer and the overall survival is significantly lower in patients who have high IQGAP3 expression." (PMID 32824461, 2020). "The chromosome region 1q22 that contains IQGAP3 was also found to have copy number gains in gastric cancer." (PMID 32824461, 2020). "Our studies showed that elevated IQGAP3 expression plays an important role in the migration and invasion of gastric cancer cells through interaction with major cytoskeletal and cell adhesion proteins." (PMID 32824461, 2020). "In line with their results, we identified the overexpression of IQGAP3 in the gastric cancer samples of both subtypes, diffuse and intestinal." (PMID 32824461, 2020). "Just recently, elevated expression of IQGAP3 was identified by immunohistochemistry (IHC) staining in the 165 gastric cancer tissues, and was significantly correlated with poor survival." (PMID 32824461, 2020). "In contrast, knockdown of IQGAP3 in two gastric cancer cell lines successfully reduced the number of invading cells and colonies in matrigel invasion and soft agar assays, respectively." (PMID 32824461, 2020). "Currently, in the TCGA database there are at least 400 gastric cancer samples with complete clinical information and RNA-seq data available, we set out to analyze the correlation between IQGAP3 expression and various clinical parameters." (PMID 32824461, 2020). "Taken together, we demonstrated that IQGAP3 plays critical roles in migration and invasion of human gastric cancer cells, and regulates cytoskeletal remodeling, cell migration and adhesion." (PMID 32824461, 2020). "In line with our microarray results, the expression of IQGAP3 was statistically significantly higher in gastric cancer tissues comparing to normal controls in both diffuse and intestinal subtypes." (PMID 32824461, 2020). "The same result was also confirmed by comparing the average expression levels of IQGAP3 between normal and gastric cancer samples in the TCGA database, comprising 415 patients (p < 0.001)." (PMID 32824461, 2020). "Recently, IQGAP3 expression was found to be related to clinical stage and was an independent prognostic classifier of gastric cancer patients." (PMID 33519444, 2020). "Immunocytochemical staining of MKN1 gastric cancer cells showed that IQGAP3 was concentrated in the cell cortex beneath the plasma membrane." (PMID 32824461, 2020).
gastric cancer (continued). "Among 23,040 genes examined, we observed overexpression of IQ-domain GTPase activating protein 3 (IQGAP3) in both types of gastric cancer." (PMID 32824461, 2020). "In this study, we have demonstrated that the up-regulation of IQGAP3 promotes invasion and migration in gastric cancer cells, most likely through interacting with e-cadherin and/or β-catenin in association with the reduction of cell-cell adhesion." (PMID 32824461, 2020). "Immunohistochemical analysis of gastric cancer tissues revealed that IQGAP3 accumulated in the cytoplasm of 23 (88.5%) of 26 gastric adenocarcinomas examined; positive staining was observed in 19 of 21 intestinal-type tumors, and in 4 of 5 diffuse-type tumors." (PMID 32824461, 2020). "The expression of IQGAP3 was found higher in stomach cancer (22/48), colorectal cancer (46/50), prostate cancer (27/32) and brain cancer (16/44) compared to the uninvolved tissue." (PMID 29073199, 2017). "The Kaplain-Meier analysis revealed significant correlation of IQGAP2 and IQGAP3 expression with the survival of the gastric cancer patients." (PMID 29073199, 2017). "In agreement with this, we showed that IQGAP3 protein localized at the spindle pole body, contractile ring and concentrated at the cleavage furrow during mitosis and cytokinesis, and also co-localized with myosin light chain in gastric cancer cells." (PMID 32824461, 2020). "Therefore, we examined the expression of IQGAP3 protein in gastric cancer, with an in-house IQGAP3-specific antibody." (PMID 32824461, 2020). "In addition, we revealed that IQGAP3 possibly plays an important role in cytokinesis in gastric cancer cells." (PMID 32824461, 2020). "In addition, we showed a co-localization of IQGAP3 and myosin light chain at the contractile ring during cytokinesis in ST-4 diffuse-type gastric cancer cell line." (PMID 32824461, 2020). "Overexpression of IQGAP3 has been observed in lung, liver, pancreatic, and gastric cancer." (PMID 33519444, 2020). "Interestingly, IQGAP3 expression in tumors was elevated since the earliest stage of gastric cancer progression and lymph node metastasis (stage 1, tumor grade 1, and N0)." (PMID 32824461, 2020). "We, thus, proposed that IQGAP3 expression may be used as a potential biomarker for early detection of gastric cancer." (PMID 32824461, 2020). "In stomach cancer, IQGAP3 staining was strong in 45.8% and moderate in 29.2% cases." (PMID 29073199, 2017). "Therefore, genomic amplification might also play a role in IQGAP3’s elevated expression in gastric cancer." (PMID 32824461, 2020). "However, the possibility that enhanced endogenous IQGAP3 in gastric cancer may permit interaction with Ras cannot be completely ruled out." (PMID 32824461, 2020). "We further confirmed that gastric cancer cell lines, MKN1 and TMK1, expressed a high level of IQGAP3, whose expression was hardly detectable in 293T and NIH3T3 cells (data not shown), suggesting that high expression level of IQGAP3 might be associated with gastric cancer tumorigenesis." (PMID 32824461, 2020). "In contrast, suppression of IQGAP3 by short-interfering RNA (siRNA) markedly reduced invasion and anchorage-independent growth of MKN1 and TMK-1 gastric cancer cells." (PMID 32824461, 2020). "In this study, we found that IQGAP3, a member of the IQGAP gene family, was significantly up-regulated in human gastric cancer starting from the early stages of tumor progression." (PMID 32824461, 2020). "In contrast to IQGAP3, IQGAP2 expression was low in colorectal (42/53) and stomach cancer (23/47) whereas the expression was high in prostate (28/32) and brain cancer (19/49) in tumor tissue compared to uninvolved tissue." (PMID 29073199, 2017). "We further identified that genetic alterations of IQGAP3 in gastric cancer were not uncommon; at a frequency of 13% of which the majority were up-regulation of mRNA expression." (PMID 32824461, 2020).
gastric cancer (continued). "In line with the literature, our results showed that IQGAP3 plays important role in cell migration and invasion but not proliferation in gastric cancer, suggesting that its function in promoting cell proliferation might be tissue-specific." (PMID 32824461, 2020). "Thus, our studies on both non-cancerous and gastric cancer cell lines provided another strong supporting evidence for the involvement of IQGAP3 in cytokinesis." (PMID 32824461, 2020). "Regarding IQGAP1 sustaining Ras activity in gastric cancer cells, IQGAP1 but not IQGAP3 mediated cell growth through an ERK1/2-regulated NF-κB activation pathway." (PMID 25398317, 2014).
hepatocellular carcinoma (12 papers, 2014 to 2025). A malignant tumor that arises from hepatocytes. "The mutation of IQGAP3 affected the prognosis of patients with hepatocellular carcinoma, with a poor OS and DFS being noted." (PMID 35274003, 2022). "IQGAP3 was previously proved to have a diagnostic value and function as a regulator of metastasis in hepatocellular carcinoma." (PMID 31223291, 2019). "The frequency of IQGAP3 alterations (>12%) was the highest in hepatocellular carcinoma, with amplification being the main type of alteration." (PMID 35274003, 2022). "IQGAP3 has also been suggested to help in screening and diagnosis by acting as a biomarker in hepatocellular carcinoma." (PMID 33519444, 2020). "IQGAP3 protein levels were significantly elevated in the plasma of hepatocellular carcinoma (HCC) patients, so the authors suggested that it can be used as a potential biomarker for detecting HCC." (PMID 32824461, 2020). "In hepatocellular carcinoma, IQGAP3 was reported to function as an important regulator of epithelial-mesenchymal transition (EMT) and metastasis by activating the transforming growth factor (TGF)-β signaling pathway." (PMID 33519444, 2020). "IQGAP3 is considered a key regulator of metastasis and epithelial–mesenchymal transition, as it activates the transforming growth factor (TGF)-β signaling pathway in hepatocellular carcinoma (HCC)." (PMID 41446602, 2025).
liver cancer (7 papers, 2016 to 2025). An epithelial or non-epithelial malignant neoplasm that arises from the liver. "Real-time PCR and western blotting revealed that IQGAP3, at both the mRNA and protein levels, was markedly overexpressed in all 9 tested liver cancer cell lines as compared to the immortalized normal liver epithelial cells." (PMID 28810875, 2017). "Furthermore, high gene amplification was observed for IQGAP3 in breast, lung and liver cancer, which further showed positive correlation with gene expression in the same." (PMID 29073199, 2017). "Similarly, the mRNA and protein levels of IQGAP3 were differentially upregulated in all 9 freshly frozen liver cancer samples as compared to the 4 non-tumor tissues, suggesting that IQGAP3 is upregulated in liver cancer cell lines and liver cancer tissues." (PMID 28810875, 2017). "Furthermore, we verified IQGAP3 expression in liver cancer cell lines and fresh tissues." (PMID 28810875, 2017). "Likewise, IQGAP3 might be playing role in initiation in lung, breast, stomach, colorectal and liver cancer whereas it supports progression of brain, prostate and kidney cancer." (PMID 29073199, 2017). "The analysis of TCGA liver cancer data showed that the expressions of AGFG1, IQGAP3, SPINK1, CXCL9, MYO1E, and POF1B were significantly increased in tumor tissues." (PMID 41578779, 2025). "In TCGA database, the liver cancer TCGA dataset (LIHC-TCGA) showed low expression of IQGAP2 (fold change = -1.02) and high expression of IQGAP3 (fold change = 4.19) in liver cancer tissues, compared to the normal tissues." (PMID 29073199, 2017). "To further investigate the mechanism by which IQGAP3 promotes migration and invasion via EMT in HCC, we analyzed gene expression array data for liver cancers using GSEA." (PMID 28810875, 2017). "We also analyzed the complementary properties of using CCT3 and IQGAP3 in combination with AFP for the diagnosis of HCC, using a logistic regression model,with “0” represents the cirrhosis group, “1” represents liver cancer." (PMID 27390551, 2016). "In addition, TCGA data analysis revealed that IQGAP3 levels were significantly upregulated in liver cancer tissues as compared to paired tumor-adjacent non-tumor tissues." (PMID 28810875, 2017). "Despite this, we found that cell lines derived from haematologic malignancies exhibit higher IQGAP2 levels than liver cancer cell lines, which does not occur for IQGAP1 and IQGAP3." (PMID 34034707, 2021).
pancreatic cancer (7 papers, 2017 to 2022). "A study showed that cell apoptosis, metastasis and Cdc42 pathways were strongly associated with IQGAP3 expression in pancreatic cancer patients." (PMID 32824461, 2020). "A recent study also proposed that IQGAP3 is a Cdc42 pathway-related protein, since knockdown of IQGAP3 in a pancreatic cancer cell line decreased the expression of Cdc42." (PMID 32824461, 2020). "Similar results were also observed in pancreatic cancer, where reduced expression of IQGAP3 resulted in early apoptosis and subcutaneous tumor growth inhibition in the mouse model." (PMID 32824461, 2020). "On the other hand, increased IQGAP3 expression is observed in lung, liver, breast and pancreatic cancer." (PMID 29073199, 2017). "Similar studies were carried out in pancreatic cancer as well wherein elevated levels of IQGAP3 in pancreatic cancer tissues correlated with increased proliferation, migration and invasion potential." (PMID 29073199, 2017). "This is the first work to show that hnRNPC binds and stabilizes IQGAP3, allowing it to play an essential role in modulating PDAC proliferation, migration, invasion, and EMT, even though IQGAP3 was previously discovered to be increased in pancreatic cancer cell lines." (PMID 35355828, 2022). "In this study, we identified that hnRNPC regulates pancreatic cancer tumorigenesis by binding and stabilizing IQGAP3, and thus, this study allows identification of novel diagnostic markers and potential targets to develop treatment strategies for pancreatic cancer." (PMID 35355828, 2022). "Furthermore, the higher expression levels of IQGAP3 correlated with poor prognosis of pancreatic cancer patients." (PMID 29073199, 2017). "Furthermore, in two pancreatic cancer cell lines (BXPC-3 and SW1990), IQGAP3 knockdown inhibited cell proliferation, migration, and invasion and induced cell apoptosis." (PMID 33519444, 2020).
colorectal cancer (5 papers, 2017 to 2023). A primary or metastatic malignant neoplasm that affects the colon or rectum. "In colorectal cancer, most of the cases (92%) showed strong staining for IQGAP3, compared to 7% in uninvolved tissue." (PMID 29073199, 2017). "In contrast to IQGAP2, significantly higher expression of IQGAP3 was found in rectal mucinous adenocarcinoma (fold change = 2.38) and colorectal carcinoma (fold change = 2.58), compared to the normal tissue." (PMID 29073199, 2017). "IQGAP3 was elevated at the tissue and cellular levels in colorectal cancer." (PMID 36831467, 2023). "This study mainly investigated the novel marker IQGAP3 at serum and tumor tissue levels compared with the markers B7-H4 and cyclooxygenase-2 (COX-2) in patients with colorectal cancer (CRC) and in healthy individuals, aiming to evaluate the diagnostic and prognostic value of IQGAP3 for CRC." (PMID 31223291, 2019). "Likewise, in TCGA datasets for colorectal cancer, IQGAP3 expression was found to be higher in colon adenocarcinoma (fold change = 2.03) and rectal adenocarcinoma (fold change = -2.25) but, not in colon mucinous and rectal mucinous adenocarcinoma." (PMID 29073199, 2017). "Oncomine database search for colorectal cancer showed 17 significant unique analyses with reduced IQGAP2 expression and two such unique analyses for IQGAP3 with increased mRNA expression." (PMID 29073199, 2017). "In the absence of availability of any survival data for colorectal cancer in Kaplain Meier plotter, SurvExpress database was used to ascertain the prognostic value of IQGAP2 and IQGAP3 in this cancer." (PMID 29073199, 2017).
ovarian carcinoma (5 papers, 2022 to 2025). A malignant neoplasm originating from the surface ovarian epithelium. "Correlations were observed between IQGAP3 expression levels and sensitivity to olaparib in ovarian cancer cells." (PMID 37370891, 2023). "IQGAP3 regulated cell proliferation via regulation of apoptosis in ovarian cancer cells." (PMID 36831467, 2023). "The knockdown of IQGAP3 increases the sensitivity of ovarian cancer cells to Olaparib, which may be accomplished by the regulation of proteins associated with DNA damage and chemoresistance." (PMID 36831467, 2023). "For instance, IQGAP3 expression has been shown to be upregulated in high-grade serous ovarian cancer, and IQGAP3 depletion inhibits the proliferation, migration, and invasion of ovarian cancer cell lines markedly." (PMID 35274003, 2022).